IL17RB (interleukin 17 receptor B)
Diseases named in the same sentence as IL17RB in open-access papers (continued):
Sharing a sentence is not in itself a finding about the gene and the disease.
infection (20 papers, 2012 to 2026). The state of being infected such as from the introduction of a foreign agent such as serum, vaccine, antigenic substance or organism. "The variant set in IL17RB demonstrated a nominally significant interaction with MPV infection (p=0.050)." (PMID 36685501, 2022). "Furthermore, the period that antigen-specific Th2 and Th9 cytokine responses and their effector function to T. spiralis infection attenuated in IL-17RB deficient mice were correlated with the delayed worm expulsion in the intestines and muscle phase of infection." (PMID 28898280, 2017). "In sea bass brain, il17ra and il17re-like were significantly decreased at 1dpi, whereas il17rb levels were increased at all the infection times, and il17ra and il17rd did at 15 and 1 dpi, respectively." (PMID 38827125, 2024). "In gilthead seabream, the expression profile in the HK was unaffected but, in the brain, il17rb, il17rd, and il17re-like were up-regulated, whereas il17rc was down-regulated to a significant extent at 1-day post-infection (dpi)." (PMID 38827125, 2024). "Transcriptome profiles of IL-25- and IL-33-treated pulmonary effector CD4+ T cells were analyzed by comparing upregulated genes in Il17rb−/− mice and wild-type mice during infection." (PMID 37337050, 2023). "When the survival of intranasally infected mice was monitored, all Il17rb-/- mice succumbed by day 10 p.i. whereas the mean-time to death for WT mice was significantly longer and 40% of the WT mice survived the infection and gain back weight." (PMID 34449811, 2021). "At day 14 post-infection, shortly after adult worms have matured, Il17rb-/- mice exhibited significantly increased egg production but equivalent adult worm burdens to the IL-25-sufficient wild-type BALB/c." (PMID 30238872, 2018). "Unlike transient induction of ILC2s during T. spiralis infection, analyses of IL-17RB expression in adaptive T helper cells revealed that IL-17RB-expressing Th2 cells were induced following 7 days of infection and persisted in the late stage of infection." (PMID 28898280, 2017). "We analyzed levels of pro-inflammatory IL-17 members (IL-17A, IL-17B and IL-17F) as well as their soluble common receptors (IL-17RA and IL-17RB) in clinically staged AE patients, that is, cured, stable, and progressive AE, and in infection-free controls." (PMID 22969818, 2012). "Interestingly, the majority of CD4+ T cell significantly induced and enriched at 14 days post-infection was IL-17RB+ ST2+ cells." (PMID 37337050, 2023). "We show that IL-17RB expression is highly affected by H. pylori in the early phase of infection." (PMID 30692510, 2019). "Furthermore, infection with WT H. pylori ex vivo, the levels of IL-17RB mRNA and protein in human primary gastric mucosa were significantly decreased compared to either no infection or infection with ΔcagA." (PMID 30692510, 2019). "However, we noted significantly reduced proportions of Siglec-F+ eosinophils and resistin-like molecule (RELM)-α+ macrophages in the PL of Il17rb–/– mice at steady-state and during the acute phase of infection (day 7)." (PMID 30238872, 2018). "In N. brasiliensis infection, ILC2s in IL-17RB deficient mice failed to expand during the early stage of infection but not in the late stage of infection." (PMID 28898280, 2017). "However, il17rb was the most up-regulated in sea bass brain upon NNV infection." (PMID 38827125, 2024). "The IL-17RB-expressing T helper cells were induced and largely co-expressed with ST2 in pulmonary C. neoformans infection at the late infection phase." (PMID 37337050, 2023). "We found that most IL-17RB+ CD4+ T cells were co-expressed with ST2, particularly at the late phase of infection." (PMID 37337050, 2023). "Compared with phosphate-buffered saline (PBS)-treated mice, IL-17RB+ CD4+ T cells were gradually increased within the lung during C. neoformans H99 infection and significantly induced at 7 and 14 days post-infection." (PMID 37337050, 2023).
infection (continued). "Using multicolor flow cytometric analysis, we first characterized the kinetics of IL-17RB, the cognate receptor for IL-25 expression on lung CD4+ T helper cells during pulmonary C. neoformans H99 infection for 3, 7, and 14 days." (PMID 37337050, 2023). "The pulmonary CD4+ T cells of C. neoformans-infected mice showed a predominant co-expression of IL-17RB and ST2, particularly at the late infection stage." (PMID 37337050, 2023). "Our scRNA-seq data has helped identify putative surface markers, such as IL-17RB and LRMP, to which antibodies can be generated to enable detailed comparison of tuft cells across tissues and at different time-points post-infection." (PMID 34880874, 2021). "The level of IgMFt 7 days post-infection (day40+7) rose significantly in WT but not in Il17rb-/- mice." (PMID 34449811, 2021). "In addition, we detected IL-17RB expression in gastric mucosa of mice infected with H. pylori, and we found IL-17RB mRNA in mouse gastric mucosa was significantly decreased compared to either no infection or infection with ΔcagA at 1 week post infection (p.i.)." (PMID 30692510, 2019). "The infection of THP-1 with virulent bacilli selectively induced IL-23 rather than IL-12 and the enhanced expression of IL-17RB and IL-17RE receptors indicating the Th17-dominated inflammatory T-cell response." (PMID 37781389, 2023).
inflammation (1 paper, 2018). Aberrant reaction of the microcirculation characterized by movement of fluid and leukocytes from the blood into extravascular tissues. "Increased expressions of IL-17RB and ST2 on mDCs are associated with enhanced local Th2 inflammation in NP, suggesting that mDCs might play a role in IL-25- and IL-33-induced type 2 responses and eosinophilic inflammation in NP." (PMID 30519393, 2018). "Furthermore, the IL-17RB and ST2 expressions on mDCs were also correlated with the IL-5 mRNA level and eosinophil numbers in NP tissues, suggesting that mDCs might play a role in IL-25- and IL-33-induced type 2 responses and eosinophilic inflammation in NP." (PMID 30519393, 2018).
IL17RB also shares sentences with these, for which no sentence is quoted: multiple myeloma (8 papers); viral infection (5); cervical cancer (3); melanoma (3); benign prostate hyperplasia (2); eosinophilia (2); glioblastoma (2); influenza (2); malaria (2); meningioma (2); non-small cell lung carcinoma (2); ovarian tumors (2); acne (1); atopic dermatitis (1); bacterial infection (1); bipolar disorder (1); brain tumors (1); bullous pemphigoid (1); colon cancer (1); coronary atherosclerosis (1); COVID-19 (1); Cowden syndrome (1); cryptococcal infection (1); cutaneous squamous cell carcinoma (1); cyst (1); cystitis (1); endometrial cancer (1); Fanconi anemia (1); female infertility (1); fibrosis (1).
A further 23 diseases each share a sentence with IL17RB in 1 paper.